ERG (ETS transcription factor ERG)
Diseases named in the same sentence as ERG in open-access papers (continued):
Sharing a sentence is not in itself a finding about the gene and the disease.
prostate carcinoma (continued). "In all, the molecular characterization of prostate cancer genes and gene function hints that several distinct molecular subsets (ERG+ vs. ERG–, PTEN+ vs. PTEN–, GSTP1+ vs. GSTP1–) may be more or less prevalent among prostate cancer cases in Black versus White men." (PMID 35104804, 2022). "A recent in vitro study suggested that it might be worth re-assessing these results according to the PTEN, GSK3b phosphorylation and FBW7 status, since genotoxic therapies induce ERG degradation in prostate cancer cells only when these three proteins are functional." (PMID 35267426, 2022). "Further characterization of the role that ERG plays in PTEN-intact prostate cancers and/or in hormone-sensitive prostate cancers may reveal their interwoven molecular dependencies and the molecular mechanisms driving disease progression potentially leading to new treatment stratification schemes." (PMID 36212399, 2022). "Interestingly, ERG is implicated several of these processes as part of its normal function and thus differences in Ras/ERK or PI3K/AKT signaling may dictate ERG function both when aberrantly expressed in prostate cancer and in its normal physiological role." (PMID 34314419, 2021). "Similarly, ERG degradation is induced by Usp9x inhibitor WP1130 in prostate cancer." (PMID 33613844, 2021). "The TMPRSS2-ERG fusion gene arising from genetic rearrangement (fusion of encoding transmembrane protease serine 2, TMPRSS2 gene, and EST-related gene, ERG) has also been a central focus in prostate cancer, which leads to aberrant expression of the ETS transcription factor ERG." (PMID 34630112, 2021). "Therefore, it is possible that treatment of ERG-positive prostate cancer with TLR4 inhibitors could simultaneously inhibit ERG function and decrease resistance to chemotherapy." (PMID 33554122, 2021). "Therefore, we hypothesized that this pathway might be involved in ERG-mediating chemoresistance to docetaxel in prostate cancer cells." (PMID 33425737, 2020). "Interestingly, we have discovered a novel way that induces ERG expression in prostate cancer." (PMID 33425737, 2020). "In the present study, we selected TMPRSS2:ERG fusion as it represents the most common genomic alteration in prostate cancer, 11 chromosomal deletions because deletions are the next most prevalent genomic alterations in prostate cancer and tumor cell proliferation." (PMID 33195694, 2020). "Moreover, blocking FGF2 by using PD173074 could reverse the enhancing effects of HUVEC on ERG expression and docetaxel resistance in prostate cancer cells." (PMID 33425737, 2020). "We detected n = 40 fusion-positive cases (7.7%) with TMPRSS2::ERG in prostate cancer being most prevalent (n = 9/40; 22.5%), followed by other gene fusions identified in cancers of unknown primary (n = 6/40; 15.0%), adenoid cystic carcinoma (n = 7/40; 17.5%), and pancreatic cancer (n = 7/40; 17.5%)." (PMID 31491926, 2019). "The significant up-regulation of ROCK1 in cancers harboring the TMPRSS2:ERG fusion fits with an earlier report describing increased expression of ROCK’s upstream regulator Rho guanine diphosphate dissociation inhibitor beta (ARHGDIB) in ERG positive prostate cancers." (PMID 31557128, 2019). "The observed comparable proportion of genomic repeat regions within the TMPRSS2 and ERG breakpoint cluster region to other mesenchymal tumors is an important prerequisite for the design of tumor-specific primers and probes for a highly sensitive therapy monitoring in prostate cancer patients." (PMID 31915468, 2019). "In all, our present study suggests that the concomitant increased expressions of both ERRα and ERG, both are under a reciprocal transactivation feedback regulation between the two transcription factors, would perform a synergistic role in the advanced progression of prostate cancer." (PMID 30042415, 2018).
prostate carcinoma (continued). "We next sought to determine whether up-regulation of T:E fusion gene or T:E-expressed ERG as induced by ERRα in prostate cancer cells could be mediated by direct transactivation of its gene or indirect regulation via other ERRα-regulated downstream signaling pathways." (PMID 30042415, 2018). "Thus, T:E fusion or ERG is regarded as a key oncogene in prostate cancer." (PMID 30042415, 2018). "One of the conclusions of these studies is that mutual exclusivity between SPOP mutation and ERG rearrangement is due to functional redundancy, and that ERG stabilization is a critical downstream mediator of the oncogenic effects of SPOP mutation in prostate cancer." (PMID 29202479, 2018). "Finally, Usp9x KD in ERG-positive prostate cancer cells (VCaP) reduced NRAS protein content." (PMID 28198367, 2017). "Therefore, SOX9 expression could be used as biomarkers of the activation of other pathways known to provoke prostate cancer progression and of docetaxel response together with the results of ERG IHC." (PMID 27863438, 2016). "Thus, overexpression of ERG in prostate cancer may cause an increase in TRIM25 activity, which is mitigated by the expression of the deubiquitinase USP9X, which is required to stabilize ERG." (PMID 27626314, 2016). "A previous report on mTOR phosphorylation in prostate cancer identified a small subpopulation of p-mTOR negative patients who may benefit from mTOR inhibition by integrating mTOR phosphorylation, ERG fusion and PTEN mutation status." (PMID 27096957, 2016). "Because ERG is a transcription activator and miRNAs are emerging as crucial regulators of cancer development, we tested the hypothesis that ERG directly regulates miRNA expression in human prostate cancers." (PMID 27191272, 2016). "From the initial discovery in 2005, the TMPRSS2- ERG gene fusion has been linked to clinical outcome parameters such as early onset of prostate cancer, negative outcome in watchful waiting patients and a higher risk of disease progression in active surveillance patients." (PMID 27276682, 2016). "However, the expression of ERG and miR-205 is mutually exclusive in cultured prostate cancer cells." (PMID 27191272, 2016). "Thus, loss of miR-145 may provide a TMPRSS2-ERG gene fusion-independent means to up-regulate ERG expression in prostate cancer." (PMID 27208692, 2016). "Based on our recent observation of a particularly high frequency of ERG fusions in early-onset prostate cancer we had hypothesized, that the development of ERG fusions is supported by the genuinely higher serum testosterone levels in younger than in older patients." (PMID 27530104, 2016). "Therefore, our model may highlight a previously unknown signalling node in ERG-positive tumours that may increase the robustness and response-rates of key pathways in prostate cancer." (PMID 25560400, 2015). "There is a high concordance rate of ERG rearrangement between the SmCC of prostate and prostatic acinar components in a given patient; however, the absence of ERG rearrangement in bladder or lung small cell carcinomas supports a common origin for these two subtypes of prostate cancer." (PMID 25937998, 2015). "In addition, analysis of the ratio of Type I/Type II ERG in relation with the prevalent oncogene C-MYC may be of value as a biomarker in prostate cancer diagnosis and prognosis." (PMID 25221645, 2014). "The identification of recurrent gene fusions in common epithelial cancers—for example, TMPRSS2/ERG in prostate cancer and EML4/ALK in nonsmall cell lung carcinomas —has raised the question of whether fusion genes are pathogenetically important also in ovarian carcinomas." (PMID 24504521, 2014). "Tissue materials generated with TURP might contain an overrepresentation of transitional zone tumors and since prostate cancers originating from the transitional zone are known to be biologically different from peripheral zone tumors this could influence the effect of ERG overexpression." (PMID 24505269, 2014).
prostate carcinoma (continued). "Here, a member of the ETS transcription factor family, ERG that is typically expressed at very low levels in benign prostate epithelial cells is fused with the androgen-responsive TMPRSS2 (transmembrane protease serine 2) to generate a prostate cancer oncogene." (PMID 25988147, 2014). "Thus, the frequently observed haploinsufficiency of NKX3.1 in prostate cancer may significantly contribute to the activation of ERG protooncogene in the TMPRSS2-ERG fusion genomic context." (PMID 24418414, 2014). "The epidermal growth factor (EGF)/Src tyrosine kinase pathway also contributes to the induction of EMT in TMPRSS2:ERG positive prostate cancers, and Kao and colleagues demonstrated that this interaction may be mediated by downregulation of miR-30, which normally suppresses ERG expression." (PMID 25496077, 2014). "In addition, ERG-positive prostate cancers are strongly histone deacetylase 1 (HDAC1)-positive and there is an over-expression of wingless-type MMTV integration site family (WNT)-associated pathways and the simultaneous suppression of tumor necrosis factors and cell death pathways." (PMID 24739220, 2014). "However, it is proposed that ERG signifies a molecular class of prostate cancer and may play a role in disease progression within those tumors." (PMID 24027643, 2013). "The low prevalence of ERG gene fusion and PTEN deficiency in Chinese patients with prostate cancer suggests that alternative molecular mechanisms may play important roles in the development of prostate cancer in Asian men." (PMID 23852643, 2013). "We speculated that ERG rearrangements induce metabolic changes in prostate cancer cells." (PMID 23390522, 2013). "In addition, many studies have suggested that TMRSS2:ERG could be a prognostic biomarker for aggressive prostate cancer." (PMID 23957008, 2013). "In addition, the presence of the TMPRSS2:ERG fusion protein could be detected by immunostaining with the rabbit monoclonal anti-ERG antibody in fusion-positive vCaP prostate cancer cells captured by the device and analyzed by multiplex confocal microscopy." (PMID 22558290, 2012). "Although ERG activation mediated oncogenic processes may be bypassed in advanced prostate cancer, hormone-regulated expression of ERG has been described to persist also in castration resistant prostate cancer, supporting the importance of this rearrangement also in advanced disease." (PMID 22761906, 2012). "However, ETS gene fusions are a challenge to target and ERG mediated oncogenic processes may be bypassed in advanced prostate cancer." (PMID 22202492, 2011). "However, the prognostic value of ERG rearrangements in prostate cancer is still controversial." (PMID 21814574, 2011). "Overexpression of ERG is thought to result in increased proliferation, invasiveness and motility of prostate cancer cells, whereas protein 4.1B has been shown to oppose invasiveness and metastasis of prostate cancer cells and EHM2 to modulate adhesion of prostate cancer cells." (PMID 20860828, 2010). "Approximately 50% of prostate cancer (PCa) patients harbor fusions involving the TMPRSS2 and ERG genes." (PMID 42120493, 2026). "In prostate cancer cells, the AEG-1/SND1 complex recruited the oncogenic ETS-domain transcription factor ERG via the Tudor domain of SND1." (PMID 40282551, 2025). "Specifically, we observed racial differences in expression of prostate cancer driver gene pathways (including potential clinically actionable pathways of IFN-γ and JAK/STAT) and DNA alterations, including TMPRSS2:ERG gene fusion." (PMID 40164700, 2025). "Studies have found that in about 50% of prostate cancer cases, intronic deletions between the TMPRSS2 and ERG genes lead to the fusion of the TMPRSS2 promoter with ERG, a fusion that exists in over 90% of ERG-overexpressing prostate cancers." (PMID 39963114, 2025).
prostate carcinoma (continued). "TMPRSS2 is commonly linked to carcinogenesis by its involvement in gene fusions with the ERG gene; TMPRSS2–ERG fusion is the most prevalent chromosomal abnormality in prostate carcinoma." (PMID 40297833, 2025). "ERG and other ETS family transcription factors are over-expressed in half of human prostate cancers as a result of fusions with the promoter sequence of the androgen receptor (AR)-dependent TMPRSS2 gene." (PMID 40332161, 2025). "In prostate cancer, the most common gene fusion event is the fusion between the promoter region of TMPRSS2 and the coding region of the ERG gene." (PMID 40332527, 2025). "In a meta-analysis by Itkonen and colleagues, GUCY1A1 was identified as an AR- and ERG-upregulated target involved in the hexosamine biosynthesis pathway (HBP), which is overexpressed in clinical cases of prostate cancer." (PMID 39337539, 2024). "In over half of all prostate cancers, chromosomal rearrangements resulting in the fusion of TMPRSS2, an androgen-regulated gene, and the ETS family transcription factor ERG occur." (PMID 38914477, 2024). "Members of the PEA3 (ETV5, ETV4 and ETV1) and ERG (FEV, FLI1 and ERG) sub‐families can behave as oncogenes, with evidence of oncogenic expression in ERG and PEA3 genes occurring early on in prostate cancer development." (PMID 39410867, 2024). "These connections are crucial for the ERG-mediated base-to-lumen transition, which is necessary for the targeted action of BAF complexes, gene expression, prostate cancer cell growth, and the overall base-to-lumen transition driven by ERG." (PMID 39439799, 2024). "TMPRSS2‐ERG is a gene fusion that is commonly found in prostate cancer, which denotes the fusion of the regulatory region of the androgen‐regulated gene TMPRSS2 to the coding region of the oncogene ERG." (PMID 38379333, 2024). "Initial attempts to target ERG involved PARP inhibitors, showing promise in preclinical models but failing in clinical trials for metastatic castration-resistant prostate cancer (mCRPC) patients." (PMID 38674385, 2024). "In prostate cancer (PCa), up to 50% of cases are characterized by TMPRSS2:ERG gene fusions, in which ERG expression is driven by the androgen-responsive TMPRSS2 promoter." (PMID 38530366, 2024). "Phosphatase and TENsin homolog (PTEN), Erythroblast transformation-specific–related gene (ERG), Serine protease inhibitor Kazal-type 1 (SPINK1), and Trefoil Factor 3 (TFF3) have been identified as important biomarkers for prostate cancer." (PMID 38256434, 2024). "Background and Objectives: Prognostic biomarkers in prostate cancer (PCa) include PTEN, ERG, SPINK1, and TFF3." (PMID 38256434, 2024). "This study determined the prevalence of ERG expression and the relationship with PSA, Gleason score, and Age of prostate cancer patients in Southwestern Uganda." (PMID 38730435, 2024). "ERG is a proto-oncogene and part of the ETS transcription factor family, which has been found to be consistently overexpressed in ~50% of patients with prostate cancer (PC)." (PMID 37509339, 2023). "Given that AR-dependent transcription is a prerequisite for ERG translocation, these studies concluded that a functional CHD1 supports AR signaling transcriptome and ERG fusion development in prostate cancer." (PMID 36776288, 2023). "In prostate cancer, the most common genetic rearrangement involves the fusion of the androgen-regulated gene TMPRSS2 with the ETS transcription factor ERG." (PMID 36776288, 2023). "For instance, ASOs have been designed to induce skipping of a specific exon (i.e., exon 4) of the ETS-Related Gene (ERG), which is an oncogene, in prostate cancer cells." (PMID 37834310, 2023).
prostate carcinoma (continued). "It is worth noting that the detection rate of ERG in isolated IDC-P is a mere 7%, which is significantly lower than in “normal” prostate cancer." (PMID 38067216, 2023). "Gene fusions between androgen-regulated genes and ERG (e.g., TMPRSS2-ERG) occur in ~50% of prostate cancers, with the alteration resulting in the presence of ERG overexpression in both early and late-stage prostate cancer." (PMID 37377909, 2023). "A significant recurrent genetic event in prostate cancer, TMPRSS2::ERG fusion, occurs in approximately 50% of all cases." (PMID 38067216, 2023). "The up-regulation of ERG is observed in >50% of prostate cancer cases, due to a genetic fusion between trans-membrane serine protease 2 (TMPRSS2) and ERG." (PMID 37310937, 2023). "For example, the T2:ERG and urine PCA3 in a large cohort of prostate cancer patients to evaluate their utility as a novel cancer biomarker panel." (PMID 36765916, 2023). "Approximately 50% of prostate cancers contain a genetic fusion between the androgen-responsive TMPRSS2 gene and the ERG transcription factor gene." (PMID 37752235, 2023). "All in all, our study confirmed the strong relationship between ERG rearrangement and PTEN deletion reinforcing the theory of an interactive or cooperative role of the two phenomena in the biology of prostate cancer." (PMID 37185705, 2023). "A similar mechanism is often present in prostate cancer, where the TMPRSS2::ERG oncofusion is found in roughly 50% of tumors and MAN2A1::FER, MTOR::TP52BP1, and SLC45A2::AMACR occur at lower frequencies." (PMID 37509339, 2023). "It shares an implication in prostate cancer with ETV5, AR and ERG; while ACE2 shares its importance in the development of COVID-19." (PMID 37287057, 2023). "They show that ETS-related gene (ERG), which has been well established in diverse human cancers, through its physical interaction with AR in prostate cancer LNCaP-LnTE3 cells using PLA, induces AR aggregation and endoplasmic reticulum stress." (PMID 37435453, 2022). "In the following review, we will discuss the transcription factors FOXA1, HOXB13, GATA2, ERG, and MYC as they relate to the AR cistrome and its transcriptional output during prostate cancer evolution." (PMID 36212399, 2022). "In prostate cancer cells, EWS is necessary for ERG to induce migration and anchorage-independent growth and acts as a co-activator that is recruited by ERG at its target genes." (PMID 35267426, 2022). "In order to understand the metabolic signatures of ERG fusion-positive prostate cancer, we interrogated the transcriptome of VCaP cells having perturbations of ERG (GSE16671, GSE110656 ERG knockdown or GSE14595; GSE164859 ERG overexpression)." (PMID 35508713, 2022). "In prostate cancer, SEs force the tumor cells to become addicted to dysregulated transcription programs mediated by proteins such as BRD4, CDK7, and ERG." (PMID 36408163, 2022). "Since inhibition of SIRT1 has been reported to suppress prostate cancer growth, we silenced SIRT1 in VCaP cells to interrogate its role in ERG-PGC1α interaction." (PMID 35508713, 2022). "Besides eNOS-NO as potential targets, targeting its upstream regulators (ERRα and ERG) of eNOS-NO signaling could also be the therapeutic strategy for the management of advanced prostate cancer, particularly the aggressive cancer carrying with the TMPRSS2:ERG fusion gene." (PMID 35526071, 2022). "Utilizing the expression levels from three genes (i.e., PCA3, ERG, and SPDEF), EPI provides a risk score predicting whether a patient presenting for their first biopsy with an equivocal PSA from 2 to 10 ng/mL is likely to have GG2 or greater (high-grade) prostate cancer." (PMID 34593984, 2022). "Thus, target inhibition of ERG or TMPRSS2 may be beneficial in prostate cancer." (PMID 35547880, 2022).